ALB (albumin)
Diseases named in the same sentence as ALB in open-access papers (continued):
Sharing a sentence is not in itself a finding about the gene and the disease.
depression (continued). "More importantly, however, we found a significant association between depression and Mini Nutritional Assessment, calf circumference, and albumin, which have previously been shown to reflect nutrition levels in elderly hospitalized patients." (PMID 35959294, 2022). "In particular, our results show that cardiovascular disease, peptic ulcer disease, Mini Nutritional Assessment and nutrition-related indicators of calf circumference, and albumin were associated with depression in senile patients." (PMID 35959294, 2022). "Our findings suggest that Comprehensive Geriatric Assessment parameters, such as cardiovascular disease, peptic ulcer disease, the Mini Nutritional Assessment score, calf circumference, and albumin were associated with depression." (PMID 35959294, 2022). "Our findings suggest that Comprehensive Geriatric Assessment parameters, such as cardiovascular disease, peptic ulcer disease, Mini Nutritional Assessment score, calf circumference, and albumin, were associated with depression." (PMID 35959294, 2022). "The risk of depression in elderly patients decreased by 19.9% for each 1-point increase in calf circumference (p = 0.002), and by 13.0% for each 1-point increase in albumin (p = 0.014)." (PMID 35959294, 2022). "Small changes in albumin that correspond to depression actually reflect larger changes in nutrition levels, and albumin changes either cause depressive symptoms, which is a very important biological marker." (PMID 35959294, 2022). "Depression is linked to a decrease in levels of serum antioxidants, such as vitamin E, albumin, zinc, tryptophan, tyrosine, glutathione and CoQ10, and an increase in levels of a well-known oxidative stress marker, MDA." (PMID 36354670, 2022). "In the present study, we found that serum albumin was inversely associated with depression in CLD patients." (PMID 34983435, 2022). "We found that patients with a higher burden of underlying disease in general, depression in particular, and low albumin levels in a blood test were more likely to develop infection." (PMID 34160237, 2021). "Other studies have also found that comorbidity, poor nutritional status, low albumin level, cognitive function and depression increase the risk of UH." (PMID 35008291, 2021). "Frailty was associated with lower serum creatinine, haemoglobin and albumin, cognitive impairment (as a categorical variable) and depression (as categorical and continuous variables)." (PMID 32850137, 2020). "Lower serum albumin levels contribute to oxidative stress dysregulation and an increased inflammation that are associated with depression and lower antioxidant capacity." (PMID 32658906, 2020). "Third, a few key questions in the WHOQOL-BREF questionnaire, including questions 10, 14 and 15, but not the total score, are associated with mortality independently from depression, age, gender, education, albumin, alkaline phosphatase and glucose levels." (PMID 28931925, 2017). "This suggests that the composite measure of cellular health and body composition captured by PhA may offer a more holistic and robust indicator of depression risk than albumin alone." (PMID 40995176, 2025). "Spearman analyses showed inverse associations between albumin and calcium with depression and anxiety, and a direct association between β2-microglobulin and depression, suggesting a potential nutritional–inflammatory pathway underlying emotional vulnerability in HD." (PMID 41463102, 2025). "The Spearman correlation and logistic regression analyses revealed the potential associations between depression and several factors, including comorbidities, albumin, PhA, skeletal muscle index, fat free mass, total body water, and extracellular water/total body water (p < 0.05)." (PMID 40995176, 2025).
depression (continued). "In contrast, AGR integrates inflammatory status (via globulin) and nutritional status (via albumin), providing a dual mechanism for assessing depression risk and potentially making it more suitable for predicting depression in specific populations such as cancer patients." (PMID 40276074, 2025). "Meanwhile, the ALFF in left inferior temporal gyrus was negatively correlated with obsessive compulsive (r = −0.348, p = 0.028), depression (r = −0.344, p = 0.003), and anxiety (r = −0.388, p = 0.013), but positively associated with serum albumin (r = 0.338, p = 0.033)." (PMID 40963810, 2025). "Therefore, this study aims to systematically evaluate the association between albumin-globulin ratio and the risk of depression in American adults using the National Health and Nutrition Examination Survey (NHANES) data." (PMID 39421614, 2024). "Lower albumin levels may reflect overall deteriorating nutritional status, which is associated with an increased risk of depression." (PMID 39421614, 2024). "However, there has been little investigation into the association between depression and serum albumin levels in community-dwelling people with a large sample size." (PMID 37880606, 2023). "As a result, our research sought to evaluate the association between depression and serum albumin and whether this relationship is dependent on several potential confounders." (PMID 37880606, 2023). "We also found that serum albumin was negatively associated with depression." (PMID 36653784, 2023). "Reduced albumin levels in patients in remission from depressive disorder may increase the risk of depressive relapse." (PMID 37340352, 2023). "Albumin levels gradually increase after antidepressant treatment, and lower albumin levels in patients in remission from depressive disorder may increase the risk of depressive relapse." (PMID 37340352, 2023). "The present study explored the association between serum albumin and depression in CLD patients and whether the association varied in different liver histological stages." (PMID 34983435, 2022). "These may explain why the association between serum albumin and depression was significant at fibrosis stage." (PMID 34983435, 2022). "If there is an independent association between serum albumin and depression, it may suggest that serum albumin is a useful biomarker in identifying CLD patients at risk of developing depressive symptoms." (PMID 34983435, 2022). "Of 20 variables, seven key predictors were selected for the model, including four continuous variables (age, serum albumin level, number of hypnotics and sedatives drugs, and total number of drugs) and three categorial variables (neurologic disorders, depression, and fall-down risk)." (PMID 35761274, 2022). "First, this study is a cross-sectional research; thus, it is unclear whether there is a causal association between serum albumin and depression among CLD patients." (PMID 34983435, 2022). "In conclusion, we identified three laboratory parameters, namely CD4+/CD8+ T cell ratio, albumin concentration, and M%, that were associated with the severity of the depressive disorder, and constructed a novel joint index to discriminate disease severity more objectively and sensitively." (PMID 35395781, 2022). "Here, the baseline features of the weighted Elixhauser score, depression, and serum albumin levels of <2.5 g/dl were associated with an increased risk of subsequent Klebsiella infection, and the use of pressors/inotropes showed a borderline association with increased risk." (PMID 34160237, 2021). "Here, the weighted Elixhauser score, depression, and serum albumin levels of <2.5 g/dl were again associated with an increased risk of infection, while baseline serum hemoglobin levels showed a borderline association such that reduced hemoglobin increased risk." (PMID 34160237, 2021). "A potential underlying mechanism for this relationship between serum albumin levels and depression could be explained." (PMID 32658906, 2020).
depression (continued). "According to the linear regression model, factors associated with fatigue were levels of pain (p < 0.0001), depression (p = 0.0017), appetite (p < 0.0001), drowsiness (p < 0.0001), well-being (p < 0.0001), shortness of breath (p < 0.0001), albumin level (p < 0.0001), and nausea status (p = 0.0001)." (PMID 22985058, 2012). "Albumin, synthesized by the liver, reflects not only nutritional status but also the inflammatory state of the body, Pro-inflammatory factors can cross the blood-brain barrier, causing immune dysregulation in the central nervous system and leading to depression." (PMID 40365002, 2025). "Therefore, the early detection of risk factors and the further management of depression and low serum albumin may assist physicians in preventing low serum concentrations." (PMID 36678192, 2023). "Therefore, we conceived to explore the associations between serum albumin and depression in CLD patients and whether this association differ by the liver histology, using the data of National Health and Nutrition Examination Survey (NHANES) from 2017 to 2018." (PMID 34983435, 2022). "Furthermore, decreased albumin levels have been associated with increased presence and severity of depression, possibly by contributing to a reduction in peripheral tryptophan levels and serotonin synthesis since albumin tightly binds tryptophan, a precursor of serotonin." (PMID 36432461, 2022). "In the univariate generalized estimating equations analysis, levels of albumin, log‐transformed CRP, NLR, and PLR were significantly associated with depression in pancreatic cancer patients (p < 0.05)." (PMID 40851223, 2026). "According to the permutation importance analysis, CRP, NLR, and albumin were identified as the most significant predictors of depression in pancreatic cancer patients across multiple ML models." (PMID 40851223, 2026). "Permutation importance analysis revealed C‐reactive protein (CRP), neutrophil‐to‐lymphocyte ratio (NLR), and albumin as key predictors of depression." (PMID 40851223, 2026). "Specifically, inverse relationships were observed between serum albumin and calcium levels and depression and anxiety scores, whereas β2-microglobulin showed a direct association with depressive symptoms—particularly among women patients." (PMID 41463102, 2025). "Those with both conditions had lower serum albumin compared to patients with depression alone (P = 0.016) or either condition independently (P = 0.015)." (PMID 41446305, 2025). "In men, albumin showed consistent inverse correlations with all three DASS-21 domains, and calcium was inversely associated with depression, reflecting a pattern compatible with a primarily nutritional profile." (PMID 41463102, 2025). "Multifactorial analysis indicated that age, cognitive impairment, depression, illness recurrence, living alone, albumin, total cholesterol, prothrombin time, and homocysteine are significant factors for moderate and high levels of oral frailty." (PMID 41450526, 2025). "For example, uric acid levels drop in depression and increase with treatment, as do albumin, zinc, CoQ, and vitamin C." (PMID 40428308, 2025). "Studies have demonstrated that albumin levels were significantly lower in patients with depression compared to healthy controls, underscoring its potential role in this condition." (PMID 40182647, 2025). "Other findings of our study were the correlations between declining cognitive status and depression, low serum albumin, and high serum CRP, confirming the results of previous studies." (PMID 40565866, 2025). "Patients with baseline anxiety showed a significantly greater reduction in HADS-A scores after adjusting for baseline pain status, albumin, and depression scores (β = 1.811, p < 0.001)." (PMID 41169418, 2025). "Although research on the roles of neutrophil percentage and serum albumin in depression is expanding, existing studies predominantly focus on isolated biomarkers and lack a multidimensional integrated analysis." (PMID 40182647, 2025).
depression (continued). "The PLS-SEM model confirmed that depression, anxiety, and stress converged onto a latent construct—Global Psychological Distress (GPD)—which showed inverse associations with albumin and calcium and a direct association with β2-microglobulin." (PMID 41463102, 2025). "Demographics, osteolytic lesions, infections, fatigue, depression, and biomarkers (albumin, creatine kinase, C-reactive protein, high-density lipoprotein, low-density lipoprotein and pro-brain natriuretic peptide) were compared in exercise vs. control cohorts." (PMID 40196920, 2025). "Age, cognitive impairment, depression, albumin, prothrombin time, cholesterol, homocysteine, multiple episodes, and living alone all significantly influenced the subtypes." (PMID 41450526, 2025). "RAR demonstrated superior diagnostic accuracy for depression compared to RDW and albumin independently." (PMID 39950171, 2025). "The literature provided evidence of a correlation between serum albumin levels and depression among various cohorts, including HIV patients, stroke survivors, individuals with chronic liver disease, elderly females, and community-dwelling populations." (PMID 39950171, 2025). "This study evaluated the correlation between nocturia, depression, and cognitive function in older adults and the mediating effect of albumin and hemoglobin on this correlation." (PMID 40672414, 2025). "LGBM provided the best discrimination for CKM–depression comorbidity and consistently highlighted albumin and family PIR as dominant predictors, with anthocyanidins contributing additional but smaller predictive information (as confirmed by NRI and IDI)." (PMID 41310757, 2025). "Previous studies have indicated that serum albumin levels are significantly lower in individuals with depressive disorders compared to healthy controls, and these levels are correlative with the severity of diseases." (PMID 39950171, 2025). "This cross-sectional study aimed to investigate potential biomarkers of oxidative stress by analyzing serum thiol-disulfide homeostasis (TDH) and ischemia-modified albumin (IMA) levels in children who have been diagnosed with major depressive disorder (MDD)." (PMID 39219868, 2024). "Multiple studies reveal that albumin quantities in depression patients are significantly decreased relative to normal control groups." (PMID 39421614, 2024). "Depression is closely related to immune activation and increased inflammation markers, and albumin levels decrease with inflammation." (PMID 39421614, 2024). "Among the volatile metabolites, 142 showed promising potential in treating insomnia, anxiety, and depression, implicating various biological and signaling pathways, predominantly ALB and TNF targets." (PMID 38774207, 2024). "Although studies have shown that patients suffering from depression show significantly decreased albumin levels, while their α1-globulin, α2-globulin, and β-globulin levels are notably higher." (PMID 39421614, 2024). "Reduced albumin levels also reduces the availability of the essential amino acid tryptophan, which affects the production of 5-hydroxytryptamine, which is a depression-related neurotransmitter." (PMID 37340352, 2023). "We found that frontal WMH volume was statistically significantly associated with long-term cognitive impairment in ALS patients after adjustment for NIHSS score, albumin, and depression." (PMID 37881309, 2023). "They found a significant decrease in serum fluid balance indices during manic episodes compared to depressive episodes in the form of lower concentrations of hematocrit, sodium, and serum albumin." (PMID 37933420, 2023). "The literature supported evidence of a link between serum albumin and depression in groups of stroke survivors, HIV patients, elderly women, and chronic liver disease patients." (PMID 37880606, 2023).
depression (continued). "This study found that total protein serum and serum albumin concentrations were significantly lower in major depression and treatment-resistant depression cases than in healthy controls." (PMID 37880606, 2023). "There is also new data linking low blood albumin levels to depression symptoms in diverse categories of psychiatric patients, including those who have schizophrenia and those who attempted suicide." (PMID 37880606, 2023). "Serum albumin can carry and transport these molecules and indirectly mediates the effects of other molecules on depression." (PMID 37340352, 2023). "Using descriptive statistics for depression distribution and multivariate logistic regression analysis, the connection between albumin levels and depression was investigated." (PMID 37880606, 2023). "Age, ASA grade, depression, emergency surgery, duration of anesthesia, WBC count, serum albumin level, and antipsychotic drugs were independent risk factors for POD." (PMID 36217732, 2023). "In other words, the severity of depression was found to significantly increase with decreasing in the level of the serum albumin." (PMID 37880606, 2023). "As compared to the control group, men with depression showed significantly higher levels of gamma-glutamyl transferase, glucose, and triglycerides, and lower levels of albumin and total bilirubin." (PMID 36653784, 2023). "As compared to the reference group of individuals with the lowest amount of albumin, those in the second quartile had a significantly lower odds ratio for depression." (PMID 37880606, 2023). "A study found that after adjusting the effect of albumin and chloride concentrations on thyroid hormone binding in plasma, the correlation between thyroid hormone index and depression became insignificant." (PMID 38179254, 2023). "The odds ratios (ORs) for depression were significantly lower in the third and fourth quartiles of serum albumin concentration compared to the first quartile (OR = 0.64 and 0.66, respectively; P values = <0.001 and <0.001, respectively)." (PMID 37880606, 2023). "After taking nutrition and liver function into account, the levels of serum albumin in Taiwanese individuals with severe depressive disorder were found to be considerably lower than those seen in normal controls." (PMID 37880606, 2023). "The results of the multivariable logistic regression model indicated that BMI, upper arm circumference, calf circumference, and albumin were significantly correlated with depression (p < 0.05)." (PMID 35959294, 2022). "In this review, lower albumin levels due to poor nutritional status contributed to depression among T2DM patients." (PMID 35457752, 2022). "Five factors (CCI score, depression, preoperative serum albumin, complications) with a p-value <0.1 in univariate analyses were included in multivariate logistic analyses." (PMID 36171818, 2022). "Covariate measures included traditional cardio-metabolic and vascular risk factors, medication therapies, Geriatric Depression Scale (GDS), Mini-Mental State Exam (MMSE), and blood biomarkers (haemoglobin, albumin, white blood cell counts and creatinine)." (PMID 36121826, 2022). "Albumin level has been reported to be significantly lower in patients with major depressive disorders." (PMID 34983435, 2022). "Depression and schizophrenia (SCH) were accompanied by an acute phase response (APR) that was implicated in the alterations in total protein (TP), albumin, and globulin levels." (PMID 35958662, 2022). "UHPLC-Q-EOMS was employed to identify 59 major components of TCEF, and network pharmacology analysis was used to screen 48 active components of TCEF for treating depression, corresponding to 139 relevant targets, including ALB, AKT1, TNF, ESR1, and CTNNB1." (PMID 36506595, 2022). "BMI, upper arm circumference, calf circumference, and albumin were lower in the depression group than in the non-depression group (p < 0.05)." (PMID 35959294, 2022).